IDH1 (isocitrate dehydrogenase (NADP(+)) 1)
Diseases named in the same sentence as IDH1 in open-access papers (continued):
Sharing a sentence is not in itself a finding about the gene and the disease.
glioma (continued). "In this study, we investigated the value of radiomics in predicting the IDH1 genotype of high-grade glioma by studying the radiomic prediction model of preoperative-enhanced MR images." (PMID 33163535, 2020). "The frequencies of BMDMs observed in the IDH1 WT glioma tumor microenvironment (TME) was higher than BMDMs frequency in the TME of IDH1-mutant gliomas, which is associated with better prognosis." (PMID 33374253, 2020). "The skewed distribution of IDH1 genotypes have been acknowledged in literature; studies with low grade gliomas involved predominantly IDH1 mutants and studies with glioblastomas involved predominantly IDH1 wildtypes." (PMID 33121211, 2020). "U87 and U251 have also been used to overexpress IDH1 wt and R132H, as well as to study the mechanism in glioma and the behavior of the cells." (PMID 33221817, 2020). "The difference between the OS of IDH1 mutant glioma and IDH1 wild type glioma were significant, which was statistically significant." (PMID 32582544, 2020). "As for apoptosis, glioma cells containing mutant IDH1 exhibit more apoptosis upon the inhibition of Bcl-xL, thus being more vulnerable to this inhibition." (PMID 31847543, 2020). "Subsequently, a large number of studies showed significant differences in prognosis between IDH1-mutant and wild-type gliomas." (PMID 33163535, 2020). "Previous studies have confirmed the role of IDH1 and IDH2 driver mutations in tumorigenesis of AML and gliomas." (PMID 32333643, 2020). "the objective was to evaluate the impact of IDH1 R132H mutation, MGMT methylation and PD-L1 expression in high grade glioma that received standard therapy (surgery, radiation and chemotherapy) to overall survival (OS)." (PMID 33282092, 2020). "IDH1 mutant type glioma was more inclined to cross the midline to invade contralateral hemisphere (p = 0.001)." (PMID 32582544, 2020). "So far, only a handful of IDH1mut glioma models have been described, which all suffer from poor reproducibility, a long development time and/or changes in IDH1 status." (PMID 33009951, 2020). "In this study, a biclassification model was established to evaluate IDH1-mutant and IDH1 wild-type gliomas by combining radiomic label features with histopathology." (PMID 33163535, 2020). "Frontal lobe involvement, oligodendroglial histology, lower Ki67 expression, WHO grades II and III gliomas, and methylated O6-methylguanine-DNA methyltransferase (MGMT) promoters were significantly associated with the presence of IDH1 mutations." (PMID 32856857, 2020). "It has been demonstrated that wild-type IDH1 (IDH1wt) gliomas are characterized by lower levels of d-2HG compared to heterozygous IDH1mut tumors depending on the loss of the wild-type allele." (PMID 32824685, 2020). "Here we demonstrate CASC2 acting as a tumor suppressor and likely interacting with miR-21 in IDH1 wild type gliomas." (PMID 33120918, 2020). "Another ongoing phase 1 clinical trial is currently enrolling patients with IDH1-mutant gliomas that have transformed into GBM to investigate the concurrent administration of the PD-L1 inhibitor avelumab and hypofractionated radiation therapy (NCT02968940)." (PMID 32291392, 2020). "FTL expression was significantly higher in IDH1/2 wildtype gliomas when compared with IDH1/2 mutant gliomas in TCGA and Rembrandt." (PMID 32677981, 2020). "To overcome these limitations for our IDH1-mutant gliomas, we performed exome sequencing on PDCs, scPDCs, and PDX samples along with multiple tumor tissue samples and germline normal DNA, for a total of 28 exomes across the 2 patients." (PMID 32904945, 2020).
glioma (continued). "A previous study found that tumor cells invaded areas remote to the primary glioma site along white matter fibers based on immunohistochemistry for IDH1-R132H in high-grade glioma." (PMID 32507763, 2020). "Increased C1RL expression accompanied the IDH1-wt phenotype in both lower grade glioma (LGG) and GBM." (PMID 32993564, 2020). "CNS-invading phagocytes in the TME of IDH1-mutant glioma were predominantly composed of monocytes and low frequencies of BMDMs." (PMID 33374253, 2020). "To note, most samples were of Isocitrate dehydrogenase-1 (IDH1) wild type molecular status and all were grade IV glioma." (PMID 32698368, 2020). "The Hallmark bile acid metabolism pathway includes IDH1 and IDH2, which also have known glioma associations." (PMID 33081688, 2020). "The implications of molecular biomarkers IDH1/2 mutations and MGMT gene promoter methylation were evaluated for prognostic outcome of glioma patients." (PMID 33552543, 2020). "For instance, the integrative analysis of the glioma using survClust revealed a small novel subtype characterized by CDKN2A deletion and IDH1/2 mutation, whereas the individual platform analysis mostly agreed with previously known subtypes." (PMID 33272320, 2020). "The IDH1 mutation occurs frequently in grade II and III gliomas, and indeed, when considering only the samples positive for IDH1R132H, the median RSK1 levels were also higher in GBMs than in LGG." (PMID 31701625, 2020). "The detection of several molecular markers, including IDH1 mutation, 1p/19q codeletion, MGMT promoter methylation status, and EGFR amplification has been applied with clinical diagnoses of gliomas." (PMID 33692940, 2020). "Except for Classical subtype in GSE16011, glioma with wild type IDH1 harbored higher EFEMP2 transcriptional levels in each subtype of these three datasets." (PMID 32396873, 2020). "Using KM analysis, OS of glioma patients was evaluated when compared between IDH1/2 mutants versus wild type by multivariate analyses." (PMID 33552543, 2020). "In this study, we explored IDH1, IDH2, and TERTp mutation status in a cohort of patients with gliomas from the WHO grade II to IV to identify the frequencies of these mutations in Chinese patients with gliomas." (PMID 32146731, 2020). "In this proof-of-concept study, Fourier transform infrared spectroscopy was used to determine the IDH1 molecular status in fixed glioma sections." (PMID 33302429, 2020). "This is consistent with previous findings that IDH1 mutations are prevalent in LGG, which constituted a majority of immunity-low gliomas." (PMID 33246490, 2020). "Point mutations at codons Arg132 of the IDH1 gene and Arg172 of the IDH2 genes were identified in 25 out of 60 (41.7%) gliomas." (PMID 32599896, 2020). "For gliomas, mutation at Arg132 of IDH1, and at the analogous codon Arg172 of IDH2, represents early initiating events that drive the evolution of low-grade glioma, including grade II to III astrocytoma and oligodendroglioma." (PMID 32280672, 2020). "IDH1 alterations were mostly found in the lower grade glioma (LGG) TCGA cohort in cBioPortal, with 78% of all LGG samples having alterations in this gene (data not shown)." (PMID 33333852, 2020). "IDH-1 status is a reliable biomarker in predicting glioma prognosis, and it correlates with CpG island methylation." (PMID 32642801, 2020). "MRS was used to serially monitor for a decrement of D-2HG levels in gliomas in a Phase I clinical trial of a new mutant IDH1 inhibitor." (PMID 33193439, 2020). "This suggested that elevated LSP1 expression was more common in IDH1 wild-type glioma and further reflected different biological genetic background between these two kinds of tumors." (PMID 32003759, 2020).
glioma (continued). "Multiple mutations in IDH isoenzymes IDH1 and IDH2, which normally catalyze oxidative decarboxylation of isocitrate to α-KG, have been shown to occur frequently in gliomas and acute myeloid leukemia." (PMID 32252351, 2020). "It was recognized that gliomas bearing IDH2 mutants accumulated more 2HG than those with IDH1 mutants." (PMID 31847543, 2020). "In summary, this study provides a novel approach to model IDH1 mutant glioma that complements existing models." (PMID 32946483, 2020). "Highest yield for screening includes recurrent post-TMZ gliomas with MGMT promoter methylation and/or IDH1 mutations." (PMID 32051040, 2020). "By contrast, in IDH1/2 wild-type gliomas, we have found a direct correlation between the presence of vascular alterations and the entrance of leukocytes into the tumors." (PMID 33147752, 2020). "The AC/DC methodology has potential for clinical translation as demonstrated in the mutant IDH1 glioma patient." (PMID 32929121, 2020). "Findings of our methods are validated by finding that for LGG, IDH1 and IDH2 mutations are selected, given the well-known prognostic value of mutations in these genes for predicting glioma survival." (PMID 33081688, 2020). "Patients’ age, KDELC2 expression, IDH1, ATRX, neurofilament, p-AxL, Nur77, H3Lys27, and PDGFRA were associated with glioma patients’ overall prognosis." (PMID 32927743, 2020). "Motivated by the observation that IDH1 wild type gliomas formed separate subclusters, we determined genes that differed between IDH1 mutant and wild type astrocytomas." (PMID 32604718, 2020). "It is well known that the wild type and mutant form of IDH1 have important impact on the regulation of local immune response and tumorigenesis in glioma." (PMID 32003759, 2020). "Somatic mutations in the human cytosolic isocitrate dehydrogenase 1 (IDH1) gene are a frequent feature observed in gliomas." (PMID 33302429, 2020). "We found that IDH1 (R132H) mutant gliomas had a mean score of 1.31 ± 0.31 (SEM) while IDH1 wild-type gliomas had a mean score of 2.36 ± 0.21 (SEM), significantly differing with a two-tailed P value of 0.0063." (PMID 32651364, 2020). "Previous studies showed that IDH1 R132H mutation was present in 80% of WHO grade II and III gliomas but less than 5% of primary glioblastoma." (PMID 33282092, 2020). "IDH1 mutants were observed in 23 (60.5%) of the 38 MGMT promoter-methylated glioma cases compared with wild-type 15 (39.5%), while six (27.3%) IDH1 mutants were found in 22 unmethylated cases versus 16 (72.7%) wild-type cases." (PMID 33552543, 2020). "Another similar clinical trial on IDH1 DC vaccine for glioma treatments is also under investigation in China (ClinicalTrials.gov identifier: NCT02771301)." (PMID 33767690, 2020). "Among gliomas, somatic mutations in the genes IDH1 and 2 occur in about 80% of grade II-III gliomas and secondary glioblastoma (GBM), while they are very rare in grade IV glioblastomas." (PMID 32316617, 2020). "According to 2016 WHO criteria, except for diffuse astrocytic and oligodendroglial tumors, the IDH1 genotypes and status of chromosome arms 1p and 19q have been incorporated into the classification of gliomas." (PMID 33229627, 2020). "CD73 expression was upregulated on immune cells by 2-hydroxyglutarate in IDH1 mutant glioma patients." (PMID 32721947, 2020). "The VEGF expression and IDH1 genotypes of 56 glioma samples in our hospital were assessed by immunohistochemistry." (PMID 33425744, 2020). "IDH1 mutant glioma was significantly more likely to exhibit homogeneous signal intensity (p = 0.009) and less contrast enhancement (p = 0.000) on MRI." (PMID 32582544, 2020). "Cluster I was characterized by enrichment of mutations in IDH1 (52%, FDR = 1.42 × 10−8) and ATRX (27%, FDR = 0.0232), consistent with their predominance in glioma samples." (PMID 33194713, 2020).
glioma (continued). "Even if this work was mostly performed in leukemia cells, and all mechanistic demonstrations were made in that context, the authors also showed that R-2HG can inhibit the proliferation of a panel of glioma cell lines, all IDH1/2 wild type." (PMID 32316617, 2020). "In a total of 108 glioma patients, VAP-1 expression and VAP-1/CD163 coexpression were both correlated with age, grade, survival, and IDH1 mutations." (PMID 32349342, 2020). "Based on the clinical annotations in this study, we observed, for the first time to our knowledge, that CD73 expression is increased in IDH1 mutant gliomas, and, mechanistically, we showed that it is induced by the oncometabolite (R)-2-hydroxyglutarate (2-HG)." (PMID 32721947, 2020). "Strikingly, G-CIMP tumors possess high frequency of IDH1 mutation, which occurs in almost 80% G-CIMP glioblastoma and more than 70% low-grade gliomas." (PMID 32051553, 2020). "We also noticed that IDH‐mutant or IDH‐like LIHC and PRAD samples belonged to subtypes with low ESR1 expression, while high ESR1 subtype was exclusively IDH‐wild‐type in glioma (GBM and LGG), and the expression of ESR1 was lower in IDH1 mutated samples." (PMID 32536040, 2020). "Here, we found mRNAsi was a reliable index that was significantly up-regulated in high grade glioma and LGG with IDH1 mutation by bioinformatics methods." (PMID 32725165, 2020). "For grade III glioma patients with an IDH1-mutantion or 1p/19q co-deletion, chemoradiotherapy significantly improves survival compared to radiotherapy alone." (PMID 32355162, 2020). "It was concluded that the autophagy signature-based IDH1 mutation and tumor grade (AIM-g) nomogram fitted almost all of the glioma patients for more precise and personalized survival prognostication." (PMID 32964017, 2020). "The results were in line with ours, and downregulated sPD-L1 levels tended to occur in glioma patients with IDH-1 MUT tumors." (PMID 33224142, 2020). "As examples of this, selection of 110 T2-MRI features allowed an IDH1 status to be estimated with an accuracy of 0.80 in patients with Grade 2 glioma." (PMID 33178967, 2020). "Briefly, somatic mutations affecting the R132 residue of the isocitrate dehydrogenase 1 (IDH1) or R172 residue of the isocitrate dehydrogenase 2 gene (IDH2) are often detected in WHO grade II or III gliomas and oligodendrogliomas." (PMID 32013066, 2020). "Taken together, these observations suggest that CASC2 acts as a tumor suppressor and potentially as a competing endogenous RNA (ceRNA) for miR-21, plays important role in IDH1 wild type glioma pathogenesis and patients’ outcomes." (PMID 33120918, 2020). "Somatic mutations of IDH1 have been frequently identified in many types of cancer, including approximately 80% of grade II-III gliomas, nearly 45% of secondary glioblastoma multiforme (GBM), and 33%-50% of adult primitive neuroectodermal tumors." (PMID 33262701, 2020). "Frequent driver mutations and amplifications of EGFR, including extrachromosomal ones, have also been detected in IDH1 wild-type, histologically low-grade gliomas (LGGs)." (PMID 32727536, 2020). "Apart from various genetic events, the discovery of IDH1 and IDH2 mutations has recently been the most exciting recent discovery in understanding oncogenetic events of glioma." (PMID 33552543, 2020). "The analysis of LN18 IDH1 mutant (R132H) and wild-type glioma cells demonstrated comprehensive coverage of primary metabolic pathways and revealed alterations in PPP, TCA cycle, glyoxylate and aldarate metabolism." (PMID 32433536, 2020). "Of course, a corollary of their observation should be that, in low grade, IDH1/2 mutant gliomas, the levels of FTO, kept low by R-2HG, result in an overall high level of m6A (or likely m6Am) RNA methylation, particularly relevant on MYC transcripts." (PMID 32316617, 2020).
glioma (continued). "In vitro studies have shown that IDH1 mutant cells are more sensitive to radiation therapy as compared to wild type cells and low grade and secondary IDH1 mutant gliomas show increased chemosensitivity." (PMID 32650387, 2020). "In another phase I trial, the safety of the IDH1 peptide vaccine for high-grade gliomas was also being evaluated." (PMID 33767690, 2020). "The effects of many molecules on the prognosis of glioma have been confirmed, such as IDH-1 and 1p19q." (PMID 32642801, 2020). "It is concluded that the model has a good predictive effect on differentiating and predicting IDH1-mutant and wild-type gliomas before an operation, and the combination of imaging and genomics can effectively improve the preoperative diagnostic level." (PMID 33163535, 2020). "Statistical analyses performed in IDH1-mutated tumours show that these genes were differentially-expressed between both type of grade II and III gliomas." (PMID 32218467, 2020). "The objective of this trial is to understand the role of AG-120 and AG881 in the suppression of 2-HG by comparing the concentration of 2-HG in resected and treated tumors from IDH1 mutant glioma patients with the concentration of 2-HG in untreated tumor." (PMID 32290213, 2020). "Since it has been widely recognized that IDH1 mutation is a critical driver of low grade glioma, we explored the relationship between EFEMP2 transcription level and IDH1 mutation." (PMID 32396873, 2020). "Mutations in the IDH1 or IDH2 genes have been detected in a large number of adult diffuse grade II and grade III gliomas; such high frequency has suggested a possible role for those variants as the earliest oncogenic event in these malignancies." (PMID 33282797, 2020). "Among them, 61 cases of low-grade glioma, 55 cases of high-grade glioma, 62 cases of IDH1 mutant glioma and 54 cases of IDH1 wild-type glioma." (PMID 32582544, 2020). "This is comparable to concentrations of 0.35–9 nmol/mg tissue found by using liquid chromatography electrospray ionization tandem mass spectrometry in an IDH1/2 mutant bearing gliomas versus 0.5 pmol/mg up to 0.12 nmol/mg of wt gliomas." (PMID 31847543, 2020). "The radiomic model, based on the preoperative-enhanced MR, can effectively predict the IDH1 genotype in high-grade glioma." (PMID 33163535, 2020). "This is reflected in our dataset, as 17 out of 19 (89%) low grade gliomas were IDH1 mutants and 76 out of 81 (94%) grade IV gliomas were wildtype." (PMID 33121211, 2020). "For example, the isocitrate dehydrogenase (IDH) gene mutations (IDH1 and IDH2) are detected in more than 70% of sporadic low-grade gliomas and in the majority of glioblastomas arising from lower grade gliomas." (PMID 31906320, 2020). "One of the possible explanations of the phenomenon observed consists in the fact that all glioblastoma cell cultures had wild-type isocitrate dehydrogenase 1 (IDH1) gene, while glioma cell cultures taken for the investigation occurred to be IDH1-mutant." (PMID 32731436, 2020). "Mutational analysis of TCGA data set revealed that SNPs in IDH1, ATRX, PTEN and EGFR were significantly associated with risk status in glioma." (PMID 32301283, 2020). "Lower-grade glioma patients with lower DZIP3 expression have similar survival time with GBM, while the survival time of the other patients is similar to that of the IDH1 mutation group." (PMID 33229627, 2020). "It is well established that IDH-1 MUT and IDH-1 WT gliomas have distinct tumor behavior driven by different oncogenic signals and respond differently to current treatment paradigms." (PMID 33224142, 2020). "Considering the importance of stoichiometry and functional character of proteins, we propose that in this sense, our model reflects the molecular aspect of IDH1-mutant gliomas." (PMID 32946483, 2020).